TNF (tumor necrosis factor)
Diseases named in the same sentence as TNF in open-access papers (continued):
Sharing a sentence is not in itself a finding about the gene and the disease.
vasculitis (continued). "Furthermore, we demonstrate an immunomodulatory role of the TNFα/TNF receptor system in HCV-associated vasculitis with a potential impact on the development of new therapeutic strategies." (PMID 25419735, 2014). "It has also been hypothesized that the blockade of the TNF-α signaling pathway induces a cytokine imbalance, with a shift from a T helper 1 pattern to a T helper 2 pattern, which renders the patient susceptible to vasculitis." (PMID 37176606, 2023). "Additionally, immune dysregulation or a cytokine imbalance may underlie the development of vasculitis in patients during anti-TNF therapies." (PMID 26864464, 2016). "Dermatologic reactions to TNF inhibitors typically include erythematous rashes, urticaria, and, in rare cases, vasculitis." (PMID 41158918, 2025). "Similar to TNF inhibitors, other biologic agents, such as rituximab and tocilizumab (IL-6 inhibitors), have been reported to induce vasculitis in some patients." (PMID 41158918, 2025). "Early reports indicate a 36.4% incidence of anti-TNF vasculitis in UC patients using IFX, typically developing within 6–38 weeks of treatment initiation, despite standard administration protocols." (PMID 39861147, 2025). "The relationship between the use of TNF‐α inhibitors and onset of vasculitis remains to be clarified." (PMID 40292847, 2025). "Biallelic hypomorphic variants of OTULIN underlie an autoinflammatory disorder with multiple phenotypes including vasculitis, and high levels of NF-κB, TNF, IL-1β, and IL-17 production have also been observed." (PMID 39403923, 2024). "This aligns with existing reports of TNF inhibitor-induced vasculitis, which often resolves upon discontinuation of the offending agent." (PMID 39583403, 2024). "The mechanism of this paradoxical side effect is unclear, and the role of TNFα in the development and progression of vasculitis cannot be determined." (PMID 39204132, 2024). "Complications are often due to vasculitis and endothelial cell injury, with a cytokine storm involving IL-6, TNF alpha, and IL-10 contributing to multi-organ failure." (PMID 39737257, 2024). "Vasculitis can occur denovo or related to cases with concurrent therapy such as tumor necrosis factor (TNF)-inhibitors." (PMID 39583403, 2024). "TNF inhibitors are known to be effective in managing RA, but they can paradoxically induce autoimmune conditions, including vasculitis." (PMID 39583403, 2024). "Vasculitis-induced biologic tumor necrosis factor (TNF) inhibitors have been reported, particularly cutaneous vasculitis and lupus-like syndromes." (PMID 39583403, 2024). "TNF-α induces a chronic upregulation of the neutrophil activity and an endothelial cell instability that eventually prone to a vasculitis phenotype and bone marrow disorders." (PMID 37179309, 2023). "In the first patient the appearance of suspected drug-induced IgA vasculitis after 6 years of therapy with golimumab is unusual, but cases of vasculitis after long-term use of TNF inhibitors have been reported." (PMID 38124070, 2023). "Five cases (0.6% of the patients on anti-TNF medication) of biopsy-proven vasculitis secondary to anti-TNF therapy were identified, all of which were LCV." (PMID 37176606, 2023). "We report two cases of TNF inhibitor-induced vasculitis with severe acute worsening of renal function and significant proteinuria." (PMID 38124070, 2023). "In conclusion, careful monitoring, including kidney function assessment, is necessary during anti-TNF therapy as prompt diagnosis and treatment in patients with vasculitis complications can allow satisfactory renal recovery." (PMID 38124070, 2023). "Biological drugs are currently used for the treatment of vasculitis, such as anti-TNF-alpha agents (infliximab, etanercept, adalimumab, golimumab, and certolizumab), anti-interleukin (IL)-6-receptor antibody (tocilizumab), and anti-CD20 antibody (rituximab)." (PMID 37522015, 2023).
vasculitis (continued). "Although vasculitis induced by anti-TNF therapy primarily affects the skin, related multiorgan involvement has been reported in a quarter of all patients." (PMID 37176606, 2023). "In cases of LCV where the involvement is confined to the skin, the discontinuation of the anti-TNF agent, along with a short course of oral steroids, is usually sufficient to resolve the vasculitis within a couple of months." (PMID 37176606, 2023). "This is in accordance with the findings of another study that reported 7 cases (1%) of vasculitis among 732 patients treated with anti-TNF agents for various conditions." (PMID 37176606, 2023). "As observed in our case series, LCV is the most frequent type of anti-TNF-therapy-induced vasculitis, and it predominates in women." (PMID 37176606, 2023). "This study describes a case series of vasculitis induced by anti-tumor necrosis factor (TNF) therapy in IBD patients." (PMID 37176606, 2023). "A retrospective review summarized 213 cases of anti-TNF-α agents induced vasculitis and reported the presence of systemic vasculitis was in an equally large number." (PMID 35455298, 2022). "To mimic vasculitis observed in AAV-TNF-α treated animals in a functional cellular assay with human cells, we stimulated HRMECs with TNF-α in the presence or absence of golimumab and added fluorescently labeled monocytic THP-1 cells." (PMID 35579886, 2022). "Inflammatory factors are known to induce vascular endothelial cells inflammatory response by promoting leukocyte adhesion in vasculitis, e.g. TNF-α." (PMID 35983051, 2022). "TNF‐α is the one of the leading cytokines mediating KD vasculitis, in order to better mimic the activation of macrophages in KD, we also investigated the anti‐inflammatory role of melatonin in TNF‐α‐stimulated human THP1‐derived macrophages." (PMID 35582751, 2022). "Studies have suggested that TNF-α blockers can stimulate the formation of anti-tumor necrosis factor or tumor necrosis factor-containing immune complexes in small vessels and subsequently activating the complement pathway to induce vasculitis." (PMID 36263029, 2022). "In DADA2 treatment, anti-TNF alpha agents lead to an improvement of the inflammatory vasculitis phenotype." (PMID 35774100, 2022). "More recent reports suggest the efficacy of TNF-α therapy in Behçet’s disease, a complex vasculitis characterized by superficial venous thrombus and deep vein thrombosis." (PMID 35455298, 2022). "A large number of studies have shown that in the occurrence of KD, TNF-α, IL-6, TNFR, and other cytokines exist, and these cytokines lead to vascular endothelial cell damage in KD patients, and eventually causing vasculitis." (PMID 34484292, 2021). "Treatment with anti-TNF agents has been highly efficacious in the management of the inflammatory syndrome and vasculitis." (PMID 35095905, 2021). "Altogether, we demonstrated that TNF-α expression is sufficient to induce retinal inflammation as seen by immune cell infiltrates in the vitreous and vasculitis." (PMID 34520511, 2021). "In our study, we further demonstrate that also human TNF-α can induce such inflammation, as characterized by infiltrates in the vitreous and vasculitis and – at a later stage – fibrosis and epiretinal membranes." (PMID 34520511, 2021). "In the TA pathogenesis in particular, TNF‐α was shown to exert essential functions in the progression of granulomatous inflammation, a characteristic symptom for this vasculitis." (PMID 32761844, 2020). "TNF-α is a pleiotropic inflammatory cytokine in the acute phase of Kawasaki disease and has essential physiological functions in vasculitis of KD." (PMID 32420360, 2020). "In PR3-ANCA vasculitis, levels of TNF-α, thromboxane A2 (TXA2) and CD14 were increased, while in MPO-ANCA vasculitis the C-C motif chemokine receptor 8 (CCR8) levels was higher and IL-10 expression was lower compared to controls." (PMID 33023023, 2020).
vasculitis (continued). "Studies have shown positive correlations between the elevation of EMP levels and TNF-α expression in the peripheral blood of patients with KD, suggesting that EMPs are likely to play a crucial part in the development of vasculitis in patients with KD." (PMID 31396494, 2019). "Anti-tumor necrosis factor (anti-TNF) drugs are effective in the treatment of patients with vasculitis whereas response to conventional treatment is poor." (PMID 30154798, 2018). "If inflammatory symptoms and vasculitis are predominant, anti–tumor necrosis factor agents are usually beneficial." (PMID 30692987, 2018). "The skin biopsy specimen of the right limb was diagnosed as leukocytoclastic vasculitis, which is the most common type of vasculitis that occurs during anti-TNF-α therapy." (PMID 26864464, 2016). "Taken together, these data suggest that PAD4 contributes to interstitial and perivascular inflammation as well as destructive vasculitis downstream of TNF-α in murine lungs." (PMID 27450561, 2016). "In a local Shwartzman reaction model of TNF-induced vasculitis, XBP-1 contributes to the vascular damage as shown in mice with an endothelium-specific XBP-1 deletion." (PMID 28018358, 2016). "In an in vitro model of vasculitis with HUVECs cocultured with neutrophils and stimulated with TNF or IL-1β, GCs inhibited E-selectin expression, which is involved in the damaging hyperadhesiveness of neutrophils to endothelium." (PMID 28018358, 2016). "Thus, anti-TNF therapy may be associated with the development of ANCA positive vasculitis." (PMID 24707429, 2014). "In vasculitis, anti-TNF-α are often prescribed as second/third line treatments in patients already immunocompromised by long-term use of glucocorticoids and immunosuppressive drugs." (PMID 24719524, 2014). "In the clinical setting, serum levels of proinflammatory mediators including IL-6 and TNFα have been shown to be increased in patients with an HCV-associated MC and are found to be particularly elevated during active vasculitis." (PMID 25419735, 2014). "We reviewed herein the use of anti-TNF-α therapy in different kind of vasculitis and concluded that, except for Behcet's disease, this therapeutic option has not demonstrated significant improvement in the treatment of vasculitis." (PMID 24719524, 2014). "In the medical literature, 213 cases of TNF-induced vasculitis have been reported: most of the patients had RA." (PMID 25544845, 2014). "In this study, 118 patients (the majority with RA) developed vasculitis after starting anti-TNF-agents." (PMID 25544845, 2014). "Referring to vasculitis in particular, TNFα is known to partly mediate the prothrombotic conditions implicated by systemic inflammation, and small vessel occlusion results in an amplification of local inflammatory responses." (PMID 25419735, 2014). "Preliminary data suggest that other several forms of vasculitis appear responsive to TNF antagonists (Behçet's disease, Churg-Strauss vasculitis and giant cell arteritis)." (PMID 24917817, 2014). "In a Candida albicans-derived substances (CAD) mice model, another KD vasculitis model, IL-1β, IL-6, and TNF-α are reported to be upregulated." (PMID 23606968, 2013). "At 4 weeks, the degree of vasculitis, as indicated by the total area of inflammation, correlated with TNF-α and IL-13 levels in each animal of all groups (r = 0.78, P < 0.0001; r = 0.60, P = 0.0003, resp)." (PMID 23606968, 2013). "Initially thought to have vasculitis, for which extensive investigations had been made, the patient had failed to respond to broad-spectrum immunosuppression, rituximab, or anti-tumor necrosis factor (TNF) therapy." (PMID 23421920, 2013). "In particular, CD8+ cytotoxic T cells (CD8+ Tc1 cells) and CD4+ Th1 cells are thought to contribute to the progression of lupus glomerulonephritis and vasculitis through release of inflammatory cytokines such as TNFα and INFγ." (PMID 25400916, 2013).
vasculitis (continued). "To determine the effect of the protein G-purified anti-PR3 antibodies on neutrophil function, we incubated IgG from healthy controls or patients with vasculitis with purified, tumour necrosis factor α (TNFα)-primed, human neutrophils." (PMID 22247758, 2012). "In vivo, TNF-α alters endothelium and is a potent chemoattractant for neutrophils which contributes to the pathology of venous thromboses, arteriosclerosis, vasculitis, and disseminated intravascular coagulation." (PMID 18937852, 2008). "On one hand, TNF-α can decrease IL-5 levels and eosinophilia, shifting inflammation from a neutrophil to an eosinophil bias; however, TNF-α blockade has shown no efficacy in treating anti-neutrophil cytoplasmic antibody (ANCA)-associated vasculitis (Group." (PMID 40703351, 2025). "Most reported cases of anti-TNF-induced vasculitis were in the small-vessel category." (PMID 41158918, 2025). "This highlights that immune mechanisms other than antibody formation against the biologic agent itself may be involved in the pathogenesis of TNF inhibitor-induced vasculitis." (PMID 40385904, 2025). "Thus, in patients with HS who develop vasculitis during anti-TNF therapy, prompt recognition and discontinuation of the drug are essential." (PMID 41567199, 2025). "Some authors have reported cases of TA following treatment with TNFα; blocking TNFα may contribute to vasculitis in patients whose immune homeostasis is already out of balance." (PMID 39204132, 2024). "Although a variety of drugs reportedly cause drug-induced vasculitis, such as hydralazine, minocycline, propylthiouracil, granulocyte colony-stimulating factor, and anti-TNF-α inhibitors, it is important to recognize that ICIs also can trigger any type of vasculitis." (PMID 36982715, 2023). "Thus, the decision to re-challenge IBD patients who develop vasculitis secondary to anti-TNF therapy with another TNF antagonist must be made on a case-by-case basis." (PMID 37176606, 2023). "Considering the possible class effect, if TNF inhibitor-induced vasculitis occurs, an alternative class agent may be indicated; careful monitoring is needed since cases of vasculitis recurrence after a change in the anti-TNF agent have been reported." (PMID 38124070, 2023). "Vasculitis is an unusual complication that is induced by TNF antagonists." (PMID 37176606, 2023). "Anti-TNF drugs are introduced as the drugs of choice in most cases presenting with vasculitis." (PMID 37312195, 2023). "Thus, the present study was conducted to assess the clinical features, the histologic findings, and the outcomes of patients with IBD who were also found to have anti-TNF-α-therapy-induced vasculitis." (PMID 37176606, 2023). "Thus, there is an urgent need to evaluate the clinical features, the outcomes, and the management of vasculitis attributed to the use of anti-TNF agents in the broad IBD patient population." (PMID 37176606, 2023). "Finally, to study TNF-α-induced vasculitis in human in vitro cell culture assays, we established a monocyte-to-endothelium adhesion co-culture system." (PMID 35579886, 2022). "Nevertheless, the role of anti-TNF-α agents in the treatment of vasculitis remains controversial." (PMID 35455298, 2022). "Tumor necrosis factor-α inhibitors are common treatments for the vasculitis phenotype of DADA2." (PMID 36300176, 2022). "Second, we used TNFα-stimulated HCAECs to simulate the infiltration of stromal cells in vasculitis." (PMID 36700213, 2022). "A recent single cell sequencing study revealed that monocytes are the main source of differentially expressed genes, and pro‐inflammatory genes such as IL‐1β and TNF‐α are significantly upregulated in PBMCs of KD patients, suggesting a pivotal role of monocytes/macrophages in KD vasculitis." (PMID 35582751, 2022). "TNF-α additionally led to vasculitis, fibrosis, and development of fibrotic epiretinal membranes." (PMID 36371417, 2022). "To date, 113 cases of vasculitis during anti-TNF therapies have been reported." (PMID 26864464, 2016).
vasculitis (continued). "However, by 5 months of age, a destructive vasculitis becomes prominent and this vasculitis is reduced in TNF+PAD4-/- compared to TNF+PAD4+/+ mice." (PMID 27450561, 2016). "Indeed, there is also a considerable amount of indirect evidence supporting a role of TNF-α in the pathogenesis of systematic vasculitis." (PMID 26475131, 2015). "In a review, 113 of 233 autoimmune disorder patients had vasculitis due to anti-TNF-α use." (PMID 25133007, 2014). "Inflammatory phenomena, such as the secretion of proinflammatory cytokines, including tumor necrosis factor alpha, and the excessive activation of neutrophils and monocytes triggered by vasculitis can induce the appearance of vasculitis in the form of polyangiitis with granulomatosis." (PMID 25580314, 2014). "In literature, some authors have reported cases of vasculitis during treatment with biological drugs, which gradually improved after high doses of steroids and immunosuppressive therapy and the discontinuation of anti-TNF." (PMID 25544845, 2014). "These inflammatory cells could synthesize and secrete various pro-inflammatory cytokines and chemokines, i.e., tumor necrosis factor (TNF)-α, interferon (IFN)-γ and interleukin 6 (IL-6), to activate endothelial cells causing vasculitis." (PMID 25007068, 2014). "In our report, the patient developed a condition of vasculitis during treatment with anti-TNF." (PMID 25544845, 2014). "In addition, binding of anti-TNF-α to membrane-associated TNF-α can have an agonistic action, initiating reverse signaling and processes such as apoptosis, cytokine suppression, and cell activation, which could constitute an interesting target in the treatment of vasculitis." (PMID 24719524, 2014). "Furthermore, we observed a strong correlation between the extent of the vasculitis and the plasma TNF-α levels." (PMID 23606968, 2013). "As a result, we could analyze significant differences between the drugs, and we found that anti-TNF-α treatment is the most beneficial in attenuating KD vasculitis." (PMID 23606968, 2013). "We speculate that by blocking the effect of TNF-α or lymphotoxin, etanercept may have reduced other cytokine levels, leading to the attenuation of the vasculitis." (PMID 23606968, 2013). "Fourthly, as the study population comprised only five patients with anti-TNF-therapy-induced LCV, the results cannot be generalized to the wider population, especially in terms of the optimal therapeutic strategies for use in patients with IBD-associated vasculitis." (PMID 37176606, 2023). "The proinflammatory IL-8 and TNFα may be elevated in an effort to manage the systemic vasculitis that is common in this model of NiV infection, although, in some circumstances, excessive TNFα may exacerbate vasculitis." (PMID 31166946, 2019). "The mechanism of vasculitis due to anti-TNF-α drugs is unknown." (PMID 25133007, 2014). "Besides, vasculitis due to anti-TNFα agents was reported in literature." (PMID 25133007, 2014). "Thus, our findings confirmed the critical role of TNF-α in the development of vasculitis in KD." (PMID 23606968, 2013). "The specific pathogenesis of TA remains to be clarified however, it has been suggested that the vasculitis may deteriorate via an autoimmune mechanism with infiltration of cytotoxic T lymphocytes and the release of proinflammatory cytokines such as tumor necrosis factor (TNF)-α." (PMID 22844294, 2012). "Furthermore, we have also demonstrated that the anti-TNF-α therapy that has been shown to be effective in treating some children unresponsive to IVIg therapy also dramatically suppresses the development of vasculitis in this mouse model of KD (manuscript in preparation)." (PMID 21958311, 2011). "The 2021 ACR/Vasculitis Foundation guidelines recommend treatment of TAK with glucocorticoids, followed by conventional disease-modifying antirheumatic drugs, then tumor necrosis factor (TNF) inhibitors or interleukin-6 (IL-6) inhibitors." (PMID 40746408, 2025).